MTOR (mechanistic target of rapamycin kinase)
Diseases named in the same sentence as MTOR in open-access papers (continued):
Sharing a sentence is not in itself a finding about the gene and the disease.
epilepsy (continued). "The concurrence of epilepsy in the same patient also suggests that PTEN gene, and the downstream PI3K/AKT/mTOR pathway, deserves to be further investigated in autism-epilepsy comorbidity." (PMID 24580998, 2014). "In the kainic acid status epilepticus model of epilepsy, mTOR signaling increased 1 h after injury, returned to baseline at 24 h, and increased again beginning at 3 days." (PMID 24672426, 2014). "While the exact mechanisms by which excess mTOR signaling promotes epilepsy remain uncertain, we believe that understanding the cellular impacts of this signaling provides novel insights." (PMID 24672426, 2014). "Animal models deleting PTEN, TSC1, and TSC2 consistently produce epilepsy phenotypes, demonstrating that increased mTOR signaling can provoke neuronal hyperexcitability." (PMID 24672426, 2014). "mTOR signalling has also been shown to be activated in animal models of epilepsy and in human cortical dysplasia." (PMID 25210733, 2014). "Although mTOR activation has been more studied in the FCDIIb and TSC, our observations suggest this pathway is activated in a variety of epilepsy-associated pathologies, and in varied cell types including dysmorphic neurones, microglia and immature cell types." (PMID 25005575, 2014). "Up to now there are only few clinical data reporting about efficacy and safety of mTOR inhibitors in epilepsy secondary to TSC." (PMID 24044547, 2013). "Rapamycin has anti-epileptogenic effects in kainate or pilocarpine models of temporal lobe epilepsy, where beside directly inhibiting mTOR activation, it inhibits mossy fiber sprouting, neurogenesis and the long-term development of spontaneous epilepsy." (PMID 24086344, 2013). "Different models show that beneficial effects on seizures are lost when treatment is withdrawn, suggesting that mTOR inhibitors are “epileptostatic” in only stalling epilepsy progression during treatment." (PMID 24044547, 2013). "As with epilepsy, mutations in PTEN that lead to aberrant activation of mTOR are associated with autism." (PMID 24379984, 2013). "Clinical studies of rapamycin in human epilepsy are limited, but suggest that mTOR inhibitors at least have antiseizure effects in tuberous sclerosis patients." (PMID 24044547, 2013). "Inhibition of mTOR activity during kainate-induced epilepsy decreases neuronal cell death, neurogenesis, mossy fiber sprouting, and the development of spontaneous epilepsy." (PMID 23203037, 2012). "We found that the mTOR pathway is activated in dispersed granule cells in the third stage of epilepsy in TLE mice, as well as in the sclerotic hippocampus of two patients (HS patients No. 12, 13)." (PMID 22761730, 2012). "The clinical evidence to date supports the use of mTOR inhibitors in a variety of TSC-associated disease manifestations, including SEGAs, renal angiomyolipoma, skin manifestations, and epilepsy." (PMID 23730262, 2012). "mTOR signaling also is considered to be one mechanism for seizure disorders that occur in tuberous sclerosis (TS)." (PMID 23203037, 2012). "Aberrant or significant mTOR activity is believed to interfere with normal brain function and lead to epilepsy." (PMID 23203037, 2012). "The mammalian Target of Rapamycin (mTOR) modulates protein translation and is dysregulated in Tuberous Sclerosis Complex, a disorder characterized by epilepsy and autism." (PMID 22567115, 2012). "Examining the circadian pattern of activity and expression of mTOR signaling molecules in epilepsy models, and studying the behavioral rhythm of null mice of those molecules will be valuable." (PMID 23189039, 2012). "In these mice, early treatment with rapamycin to inhibit mTOR activation prevents development of epilepsy, and later rapamycin treatment in mice that have already developed epilepsy suppresses seizures." (PMID 22761730, 2012). "In addition, a key aspect of TSC‐related epilepsy is the interaction between GABAergic signaling and mTOR dysregulation." (PMID 41090516, 2026).
epilepsy (continued). "Indeed, this manipulation led to mTOR upregulation, hypertrophic neurons, epilepsy, and anxiety-like behavior." (PMID 41255962, 2025). "This study demonstrates that postnatal DEPDC5 loss and subsequent mTOR hyperactivation without disruption of cortical migration is sufficient to cause epilepsy." (PMID 40996830, 2025). "The results of experimental studies showed that the application of rapamycin in a rat model of KA-induced epilepsy could block the abnormal activation of the mTOR signaling pathway." (PMID 41327653, 2025). "Therefore, neuroinflammation and the mTOR complex are critical pathways that are upregulated in brain cells during pharmaco-resistant epilepsies." (PMID 40949124, 2025). "This review systematically clarifies the core pathogenic mechanisms and precise treatment strategies of neurocutaneous syndrome-related epilepsy, and reveals a molecular pathological network characterized by abnormal activation of mTOR, Ras-MAPK and other signaling pathways." (PMID 40979205, 2025). "The ketogenic diet (KD) may be utilized for treating refractory mTOR-related epilepsy, according to a recent study that found KD could block mTOR signaling in rats' brains." (PMID 40546503, 2025). "Furthermore, genetic mutations for a variety of mTOR pathway genes, such as DEPDC5 in epilepsy, suggest sensitivity to mTOR inhibitors, providing evidence that genomic profiling can play a role in patient treatment selection." (PMID 40806492, 2025). "Genetically, lesion-confined mTOR-pathway mosaicism accounts for a substantial subset of FCD type II, while SLC35A2 mutations underlie mild malformation of cortical development with oligodendroglial hyperplasia in epilepsy (MOGHE)." (PMID 41155206, 2025). "Different studies have been showing that neuroinflammation and the mTOR cascade play central roles in seizures and could represent potential targets for epilepsy treatment." (PMID 40949124, 2025). "Studies have shown that mTOR signaling is commonly overactivated in epilepsy, indicating that this pathway may be significant in the pathophysiology and therapeutic management of epilepsy." (PMID 39865817, 2025). "Although the importance of pruning was classically related to schizophrenia, this mechanism can also promote hyperexcitability and epilepsy, as shown in a mice model with hyperactivation of the mechanistic target of rapamycin (mTOR) pathway in microglia (TSC1Cx3cr1 conditional knockout)." (PMID 40072465, 2025). "This may have significant implications for the treatment of diseases such as TSC, where mTOR hyperactivation leads to cortical excitation–inhibition imbalance and epilepsy." (PMID 39851507, 2025). "Sleep difficulties in particular may be driven by biological factors related to the mTOR pathway, as well as to the presence of epilepsy and use of epilepsy medications." (PMID 40514711, 2025). "Data supports a mechanism for mTOR in TANDs that is separate from epilepsy." (PMID 41255962, 2025). "mTOR is well-known for its involvement in the pathogenesis of epilepsy, as its hyperactivation leads to focal cortical dysplasia, resulting in drug-resistant epilepsy." (PMID 39860011, 2025). "This explains the role of mTOR as a therapeutic target in epilepsy." (PMID 41286527, 2025). "This may reveal a potential mechanism for the reduced inhibitory inputs observed in neurological disorders with mTOR hyperactivation including epilepsy and autism." (PMID 39851507, 2025). "Bulk RNA-seq or microarray analysis reveal gene expression changes in the mTOR pathway, neural development, synaptic plasticity, neuroinflammation, and neurodegeneration in the brain tissue of patients with drug-resistant epilepsy or rodent epilepsy models." (PMID 40026248, 2025). "Thus, pharmaceutical targeting of mTOR inhibitors for epilepsy and epileptogenesis is a topic of growing interest." (PMID 39865817, 2025).
epilepsy (continued). "This may explain why mTOR inhibition yields robust disease-modifying effects in monogenic epilepsy models but produces inconsistent outcomes in aging research." (PMID 40620657, 2025). "Experimental research has shown that mTOR inhibitors could have therapeutic potential in epilepsy treatment." (PMID 39867454, 2024). "The mTOR pathway also plays a significant role in epilepsy and epileptogenesis." (PMID 39867454, 2024). "The mammalian target of rapamycin (mTOR) was identified as a core kinase, and mTOR‐dependent local translation was shown to be critical in molecular studies of neuronal plasticity involved in the regulation of epilepsy." (PMID 37736829, 2024). "Furthermore, hyperactive mTOR signaling is found in animal models of epilepsy and the postmortem cerebral cortex of patients with epilepsy." (PMID 38365306, 2024). "Based on these studies, the mTOR pathway may be involved in the development of epilepsy under pathological conditions." (PMID 38365306, 2024). "In these animals, epilepsy develops following deletion of the mammalian target of rapamycin (mTOR) negative regulator phosphatase and tensin homolog (Pten) from a subset of dentate granule cells, while downstream Pten-expressing SST neurons are fate-mapped with green fluorescent protein (GFP)." (PMID 39497922, 2024). "Overall, mTOR inhibitors have antiepileptic effects in patients with epilepsy." (PMID 38365306, 2024). "Inhibition of the mTOR pathway by metformin and rapamycin may explain the protective role of these agents against epilepsy." (PMID 38006577, 2024). "Notably, the mTOR/MAPK signalling pathway regulates RNA-binding proteins (RBPs), and then influences the mRNA expression encoding target markers of epilepsy." (PMID 38383918, 2024). "Together, these data may explain why independent studies suggest that overactive mTOR signaling itself can lead to epilepsy." (PMID 39253727, 2024). "Additionally, prior research has indicated that the mTOR pathway is hyperactive during epileptogenesis in the cerebral cortex of humans with epilepsy or in animal models." (PMID 38365306, 2024). "The patient was placed in the epilepsy surgery pathway and considered for mTOR inhibitors." (PMID 39062615, 2024). "This indicates that mTOR signaling and neuroinflammation interact in epilepsy." (PMID 38365306, 2024). "It appears that at the molecular and cellular levels, FCD IIa and IIb are mTORopathies, and targeting the mTOR signaling pathway could be a potential treatment option for drug-resistant epilepsies." (PMID 40217486, 2024). "In addition, the disruption of exosomal activity is itself a powerful trigger for epilepsy, negatively affecting many systems, such as the mTOR system and the translation machinery." (PMID 36982355, 2023). "The TBCK syndrome is another very rare neurogenetic disorder that involves mutant TBC1 domain containing kinase (TBCK) gene (an activator of the mTOR signaling) and presents clinically as leukoencephalopathy, coarse face, neuropathy, epilepsy, hypotonia and intellectual disability." (PMID 36675042, 2023). "In genetic mouse models, hyper-activation of mTOR signaling due to loss of the upstream regulators phosphatase and tensin homolog (PTEN) or tuberous sclerosis complex (TSC) has been associated with cortical malformations and the development of epilepsy." (PMID 37880579, 2023). "Furthermore, inhibiting mTOR leads to delayed microglial activation in the hippocampus of mice with KA-induced epilepsy." (PMID 38078329, 2023). "Importantly, such phenotypic abnormalities in zebrafish embryos and larvae are rescued by a conventional mTOR inhibitor rapamycin, collectively suggesting these fish as a valuable genetic model of mTORopathic epilepsy." (PMID 36675042, 2023). "Interestingly, emerging studies have demonstrated that overactivated mTOR induces the pathogenesis of epilepsy by disrupting the formation of neural circuits and altering existing neural networks." (PMID 37221133, 2023).
epilepsy (continued). "Overall, the efficacy and safety of mTOR inhibitors are satisfactory, which suggests that this class of drugs may be a beneficial treatment option for refractory epilepsy in patients with TSC." (PMID 37221133, 2023). "Here, we discuss recent advances and current challenges in developing experimental models of mTOR-dependent epilepsy and other related mTORopathies, including using zebrafish models for studying these disorders, as well as outline future directions of research in this field." (PMID 36675042, 2023). "In the etiology of epilepsy, novel gene discoveries have moved the field beyond the known contribution of ion channels to implicate chromatin remodeling, transcriptional regulation, and regulation of the mammalian target of rapamycin (mTOR) protein." (PMID 36937533, 2023). "Other researchers hypothesize that the aberrant activation of the mammalian target of rapamycin (mTOR) is associated with both ASD and epilepsy." (PMID 36819340, 2023). "Moreover, AMPK which induces autophagy by inhibition of the mTOR pathway is also intricate in epileptogenesis and epilepsy." (PMID 37880579, 2023). "The mTOR cascade activation may be an important cause of TSC‐related epilepsy, a form of epilepsy caused by malformations of cortical development (MCDs)." (PMID 37221133, 2023). "mTOR hyperactivity occurs in neocortical pyramidal neurons and results in increased neuronal soma size, dendritic complexity, and alterations in connectivity, all of which contribute to epilepsy." (PMID 37620147, 2023). "In parallel, we measured activation of the mechanistic target of rapamycin (mTOR) because enhanced signaling of this pathway can occur in response to neuronal hyperactivity and seizures in both human and experimental epilepsy, and contributes to the pathology of FCD34 and AD." (PMID 37052232, 2023). "Emerging evidence suggests that mTOR acts as a bridge between neuroinflammation and epilepsy." (PMID 37221133, 2023). "Reduced mTOR inactivation is a key trigger of epilepsy in both clinical and animal studies." (PMID 36675042, 2023). "Thus, the exact mechanisms of how mTOR inhibitors contribute to epilepsy, as well as molecular cascades involved, remain yet unclear." (PMID 36675042, 2023). "Furthermore, autophagy dysfunction exists in epilepsy, and the impairment of mTOR‐dependent autophagy has been found to be related to the mechanism by which mTOR overactivation promotes epilepsy." (PMID 37221133, 2023). "Conversely, the inhibition of mTOR can forestall the onset of epilepsy." (PMID 40217521, 2023). "Targeting the mTOR signaling pathway provides a promising prospect for the treatment of epilepsy." (PMID 37221133, 2023). "Indeed, mTOR signaling is responsible for cell growth and survival, and alterations are related to multiple brain disorders, including neoplasms and epilepsy." (PMID 36831117, 2023). "Our data, as well as recent work correcting PI3K-dependent or TSC2-dependent epilepsies with more targeted drugs, imply that direct correction of a hyperactive node may be more effective than the simple use of rapalogs for all mTOR pathway disorders." (PMID 37741456, 2023). "The mTOR inhibitors can prevent epilepsy and reduce potential brain abnormalities." (PMID 37221133, 2023). "However, the specific mechanism behind the effectiveness of mTOR inhibitors against epilepsy remains uncertain." (PMID 36645181, 2023). "Thus, it is of great value to explore the correlation between genotype and clinical phenotype of an mTOR signaling pathway in the field of pediatric epilepsy." (PMID 36937533, 2023). "In addition, the PI3K/AKT/mTOR pathway was identified as a molecular target to control spontaneous seizure in a preclinical model of epilepsy." (PMID 36013437, 2022).
epilepsy (continued). "Recent studies have suggested that hyperactivation of the mTOR signaling pathway and abnormal autophagy activity occur in different epilepsy animal models and epilepsy-related patients, whereas inhibition of mTOR activity can ameliorate seizures in various epilepsy models." (PMID 36078029, 2022). "Moreover, ncRNAs and mTOR have emerged as potential biomarkers, as well as therapeutic targets in the management of epilepsy." (PMID 35898503, 2022). "In genetic mouse models of ASD and Dravet syndrome, tau ablation prevents epilepsy and normalizes mTOR overactivation, suggesting that reducing tau may be beneficial in these diseases via PTEN disinhibition." (PMID 35923547, 2022). "Thus suppression of the mTOR pathway is anti-epileptic and restores the normal glutamate signaling pathway that renders it a potential target in epilepsy treatment." (PMID 36286014, 2022). "This reinforces the hypothesis that dysregulation of the mTOR pathway is pivotal for the development of epileptogenesis and epilepsy." (PMID 36145334, 2022). "Furthermore, studies on genetic and acquired epilepsy models have revealed the antiepileptogenic potential of mTOR inhibitors." (PMID 36145334, 2022). "Whether the modulation of the mTOR pathway and immune responses, in terms of antiepileptogenesis effects, can lead to a new stage in the treatment of different forms of epilepsy remains to be determined." (PMID 35742889, 2022). "An activated mTOR pathway may be involved in several neurologic disorders, including epilepsy, autistic spectrum disorders, multiple sclerosis, and Parkinson’s disease." (PMID 35334932, 2022). "We show that in this model, a few neurons with increased mTOR activity can be the driving force behind MCD-related epilepsy through aberrant connectivity, resulting in increased excitability of distant nontargeted neurons, which can be reversed by blocking vesicular release." (PMID 34038402, 2021). "Therefore, FCD 2b and TSC are classified as mTORopathies, characterized by malformed cortical development and frequent epilepsy, likely representing a spectrum of diseases along the mTOR pathway." (PMID 33786950, 2021). "How increased levels of mTOR drive these neuronal changes that ultimately lead to epilepsy remains largely unknown." (PMID 34877936, 2021). "Among them, everolimus is a registered mTOR inhibitor for epilepsy in TSC." (PMID 33995061, 2021). "Some studies suggest that autophagy may induce epilepsy through the mammalian target of rapamycin (mTOR) pathway or abnormal glycogen accumulation." (PMID 33776649, 2021). "The anti-seizure effects of mTOR inhibition may also be applicable to other mTORopathies, as excessive activation of the mTOR pathway appears to be an essential pathomechanism for the development of epilepsy in all of these disorders." (PMID 34632383, 2021). "Nonetheless, the KD or low glycemic diets achieve the goal of diminishing glucose uptake and usage and may set a therapeutic stage to lessen use of mTOR inhibitors to treat epilepsies." (PMID 34358226, 2021). "In addition, inactivating mutations of RHEB or MTOR result in ASD, developmental abnormalities or epilepsy resulting from mTOR hyperactivity, although their frequency is low." (PMID 34828352, 2021). "Previous studies used widely different experimental systems (e.g., cultured neurons versus brain slices, embryonic deletion versus induced adult deletion, sparse deletion versus global deletion) to determine how increased mTOR signaling changes neuronal circuits and thus leads to epilepsy." (PMID 34877936, 2021). "mTOR inhibitors may offer an alternative therapeutic strategy in individuals with surgically inaccessible FCD or for persistent seizures after epilepsy surgery." (PMID 34632383, 2021). "These salient features in the ubtor mutant zebrafish may also be used as a preclinical model for studies and screening for compounds regulating mTOR signaling and treating epilepsy." (PMID 34309811, 2021).